BCAR4 (breast cancer anti-estrogen resistance 4)
Diseases named in the same sentence as BCAR4 in open-access papers (continued):
Sharing a sentence is not in itself a finding about the gene and the disease.
lymph node metastasis (3 papers, 2019 to 2022). "Odds ratios (ORs) and their 95% CIs were used to assess the association between lncRNA BCAR4 expression and clinicopathological features, including tumor size, differentiation, lymph node metastasis, distant metastasis, and tumor stage." (PMID 31124974, 2019). "They observed that BCAR4 expression was significantly correlated with poor OS (HR = 1.98, CI: [1.71–2.29]), p < 0.00001, and high expression levels of BCAR4 correlated with worse clinical stage, distant metastases, and lymph node metastasis." (PMID 35740618, 2022). "Overexpression of lncRNA BCAR4 was related to lymph node metastasis (OR 3.68, 95% CI: 2.25–6.00; P < .001), high tumor stage (OR 3.19, 95% CI: 1.98–5.13; P < .001), and distant metastasis (OR 3.83, 95% CI: 2.15–6.82; P < .001), but not to tumor size." (PMID 31124974, 2019). "The pooled results indicated that overexpression of lncRNA BCAR4 was associated with lymph node metastasis, high tumor stage, and distant metastasis; however, no relation was determined between lncRNA BCAR4 and tumor size." (PMID 31124974, 2019).
chondrosarcoma (2 papers, 2019 to 2020). A malignant cartilaginous matrix-producing mesenchymal neoplasm arising from the bone and soft tissue. "BCAR4 was also reported to promote chondrosarcoma cell proliferation through activation of mTOR19, a downstream target of ERBB2/ERBB3 signalling." (PMID 32193429, 2020).
liver cancer (1 paper, 2023). An epithelial or non-epithelial malignant neoplasm that arises from the liver. "For instance, lncRNA BCAR4 may promote the proliferation, migration, and invasion of liver cancer cells by directly binding to miR-1261 and targeting the anaphase-promoting complex subunit 11 (ANAPC11) gene." (PMID 36851037, 2023).
lobular carcinomas (1 paper, 2015). "Since BC cell lines with high/moderate BCAR4 mRNA expression featured CDH1/E-cadherin mutations, this tumor series was enriched for lobular carcinomas, which lack E-cadherin due to mutation or epigenetic inactivation." (PMID 26317614, 2015). "This may be related to the markedly different tumor collections (advanced stage versus early stage BCs, enrichment for lobular carcinomas) differences in assays used or the introduction of IPH-926 and human placenta tissue as a benchmark to define high BCAR4 expression." (PMID 26317614, 2015).
melanoma (1 paper, 2017). A malignant, usually aggressive tumor composed of atypical, neoplastic melanocytes. "These are: MALAT1, NEAT1, PCA3, BCAR4, lncRNA-ATB (CTD−2314B22.3) and the recently-discovered melanoma driver SAMMSON (RP11−460N16.1)." (PMID 28128360, 2017).
osteoporosis (1 paper, 2023). A condition of reduced bone mass, with decreased cortical thickness and a decrease in the number and size of the trabeculae of cancellous bone (but normal chemical composition), resulting in increased fracture incidence. "Studies showed that MALAT1 delivered by bone marrow-derived MSC-secreted exosomes could alleviates osteoporosis, and knockdown of lncRNA BCAR4 was reported to alleviate osteoporosis." (PMID 37516879, 2023).
rectal cancer (1 paper, 2022). A primary or metastatic malignant neoplasm that affects the rectum. "The expression levels of the onco-lncRNAs, including CCAT1, LOC152578, UCA1, CRNDE, PVT1, MALAT1, XLOC_000303, XLOC_006844, BCAR4, and HOTAIR, were significantly increased in the rectal cancer patients compared to the control group." (PMID 35654932, 2022).
retinoblastoma (1 paper, 2018). A malignant tumor that originates in the nuclear layer of the retina. "The results of microarray analysis showed that lncRNAs HOTAIR, CCAT1, DNM3OS, HIF1A‐AS1, MEG3 and 7SK expressions were up‐regulated, and lncRNAs PCAT1, MIR31HG, BCAR4, RRP1B and H19 were down‐regulated within retinoblastoma tissues." (PMID 30030888, 2018).
cancer (30 papers, 2010 to 2024). A tumor composed of atypical neoplastic, often pleomorphic cells that invade other tissues. "Thirteen studies with seven cancer types containing 1,128 patients were pooled together in this study, and the results indicate that promoted BCAR4 expression was markedly associated with poor prognosis of OS, but not PFS in patients with a variety of cancers." (PMID 31762809, 2019). "In conclusion, lncRNA BCAR4 overexpression is significantly related to lymph node metastasis, high tumor stage, and distant metastasis; moreover, high lncRNA BCAR4 expression is associated with poor OS in cancer patients." (PMID 31124974, 2019). "We will discuss this phenotype and whether the molecular mechanisms reported to underlie the role of BCAR4 in cancers may be relevant to its role in reproduction." (PMID 32193429, 2020). "Finally, the underlying mechanisms of BCAR4 in cancer progression still remain poorly understood, and thus more effort should be expanded to thoroughly elucidate the causative link between BCAR4 and human cancers." (PMID 31762809, 2019). "BCAR4-fusions: BCAR4-fusions were frequently found in different solid tumors, and pan-cancer analysis across 32 tumor types revealed that it was the most prevalent uncharacterized downstream fusion partner in 11 cancers." (PMID 38919532, 2024). "Cancer patients with upregulated lncRNA BCAR4 exhibited poor OS (p < 0.001), suggesting that lncRNA BCAR4 is a promising prognostic biomarker in cancer patients." (PMID 36059609, 2022). "LncRNA breast cancer antiestrogen resistance 4 (BCAR4) knockdown induces cell apoptosis and G1/S arrest, while represses cell proliferation and migration in ESCA by sponging miR-139-3p to upregulate ELAV like RNA binding protein 1 (ELAVL1)." (PMID 34516362, 2021). "Recent studies have shown that BCAR4 can promote the migration and proliferation of tumor cells in various cancers." (PMID 34122409, 2021). "But BCAR4 is also expressed in cancers, and several mechanisms have been proposed to mediate its oncogenic properties." (PMID 32193429, 2020). "A meta-analysis has been conducted by Zhao W. and colleagues 19 to demonstrate the pooled prognostic value of BCAR4 in human cancers." (PMID 31762809, 2019). "The prognostic values of lncRNA BCAR4 in cancer were assessed based on the multivariate analysis in 5 studies." (PMID 31124974, 2019). "The pooled results revealed that lncRNA BCAR4 overexpression was an independent prognostic factor for OS of cancer patients (HR 2.56, 95% CI: 1.84–3.58; P < .001, I2 = 0%)." (PMID 31124974, 2019). "Recently, it was reported that lncRNA BCAR4 was correlated with clinicopathological features and prognosis of patients with cancer." (PMID 31124974, 2019). "In conclusion, the results of our study demonstrated strong correlation of BCAR4 with unfavorable survival outcome and clinical features including metastasis and progression, implicating an independent prognostic value for BCAR4 in human cancers." (PMID 31762809, 2019). "To further investigate the downstream signaling regulating CRC malignancy, we screened the target genes of BCAR4 using Starbase v2.0 and found that miR-665, which is a critical regulator in cancers, was a promising target of BCAR4." (PMID 30962766, 2019). "As one of the promising prognostic biomarkers with high accuracy for various patients, BCAR4 has also been claimed to be involved in diverse biological processes in cancers." (PMID 31762809, 2019). "Results showed BCAR4 maintained the stemness of CSCs and promoted cancer cells proliferation and migration." (PMID 30962766, 2019). "To establish the clinical relevance of BCAR4, we investigated its relationship with tamoxifen resistance and cancer aggressiveness." (PMID 20859285, 2010). "Additionally, they performed a cancer drug library screening to identify effective inhibitors of metastatic activity induced by BCAR4 fusion." (PMID 38919532, 2024).
cancer (continued). "Research is ongoing to screen therapeutic agents for cancer with BCAR4 rearrangements." (PMID 33204025, 2021). "Based on the fact that hedgehog signaling pathways are aberrantly activated in a variety of cancer types, we speculate that lncRNA BCAR4 may also play an important role in hedgehog signaling pathways to regulate other cancer metastasis." (PMID 32929060, 2020). "Besides, expression of CSCs markers was also down-regulated by BCAR4 inhibition in ALDH+ cancer cell." (PMID 30962766, 2019). "Moreover, higher expression levels of BCAR4 in most cancer tissues compared with normal tissues were verified using TCGA and GTEx databases." (PMID 31762809, 2019). "We conducted a meta-analysis to determine the prognostic value of lncRNA BCAR4 in cancer patients." (PMID 31124974, 2019). "Therefore, we conducted this updated comprehensive meta-analysis to further investigate the prognostic role of BCAR4 in various cancers." (PMID 31762809, 2019). "However, it should be noted that well-designed clinical studies with larger sample size are still warranted to clarify the predictive role of BCAR4 in cancer prognosis in future." (PMID 31762809, 2019). "However, most individual studies evaluating BCAR4 expression in cancers remain insufficient due to the limitations in small sample size and possible controversial outcomes." (PMID 31762809, 2019). "Therefore, we conducted this meta-analysis to explore the relationship between lncRNA BCAR4 overexpression and prognosis in cancer." (PMID 31124974, 2019). "The pooled results demonstrated that lncRNA BCAR4 overexpression was significantly related to poor prognosis and could be used as an unfavorable prognostic biomarker in cancer patients." (PMID 31124974, 2019). "Thus, further high-quality studies with large sample sizes are needed to verify the function of lncRNA BCAR4 in various cancer." (PMID 31124974, 2019). "In addition, overexpression of BCAR4 facilitated the maintenance of ALDH positive cells (a type of cancer stem/initiating cells) stemness and promoted ALDH+ cells proliferation and migration." (PMID 30962766, 2019). "In addition, we compared BCAR4 expression levels between cancerous and normal tissues in patients with different kinds of cancers using TCGA and GTEx datasets to verify the expression status or levels of lncRNA BCAR4." (PMID 31762809, 2019). "The prognostic value of lncRNA BCAR4 in cancer patients has varied among studies." (PMID 31124974, 2019). "BCAR4 is a lncRNA involved in cancer progression and is expressed in bovine and human oocytes." (PMID 29396444, 2018). "In 2014, Yang reported on the lncRNA BCAR4 (breast-cancer anti-estrogen resistance 4), which simultaneously binds to the transcription factor SNIP1 (Smad nuclear interacting protein 1) and the phosphatase 1 nuclear- Targeting subunit (PNUTS), and it regulates the hedgehog/GLI2 signaling pathway." (PMID 28212533, 2017). "In one of the screens, we identified a new gene, breast cancer anti-oestrogen resistance 4 (BCAR4)." (PMID 20859285, 2010). "In a separate cohort of patients with lymph node-negative, ERα-positive cancer, and not receiving systemic adjuvant therapy, BCAR4 levels were evaluated for association with distant metastasis-free survival (MFS)." (PMID 20859285, 2010). "In addition, previous studies showed relationships between lncRNAs, including FENDRR and BCAR4, with the expression of cytokines and chemokines in cancer, which could modulate the infiltration of immune cells to the TIME." (PMID 37260772, 2023). "In addition, the pooled ORs have revealed that BCAR4 expression might be regarded as an independent prognostic biomarker for aggressiveness and metastasis in human cancers." (PMID 31762809, 2019). "Thus we hypothesized that whether BCAR4 regulated cancer progression through affecting CSC capacity and how." (PMID 30962766, 2019).
cancer (continued). "Therefore, lncRNA BCAR4 overexpression is associated with poor OS and advanced clinicopathological features, and lncRNA BCAR4 may be a novel prognostic biomarker in cancer patients." (PMID 31124974, 2019). "In our study, BCAR4 was proved to bind miR-139-3p thereby targeting ELAVL1, which was consistent with a previous research that miR-139-3p inhibited cancer progress by reducing ELAVL1 expression." (PMID 33602031, 2021). "We further proved that miR-665 was the target of BCAR4 and subsequently activated signal transducers and STAT3 signaling which is an important pathway in cancer stem cells self-renewal." (PMID 30962766, 2019). "Further, miR-665 was demonstrated to be the target of BCAR4 and subsequently activated STAT3 signaling which is an important pathway in cancer stem cells self-renewal." (PMID 30962766, 2019). "Thus, lncRNA BCAR4 may be a novel prognostic biomarker in cancer patients." (PMID 31124974, 2019). "The “MII oocyte lncRNA signature” included the lncRNAs BCAR4, PCAT1, WEE2-AS1 and TUNAR that are involved in cancer, cell cycle and pluripotency." (PMID 29396444, 2018). "ExInAtor was modeled on 1112 whole genomes from 23 cancer types deposited in GENCODE, and predicted 15 lncRNA drivers with a high confidence, of which nine were novel lncRNAs and six were known cancer-related transcripts, including PCA3, MALAT1, BCAR4, lncRNA-ATB, and SAMMSON." (PMID 38068923, 2023). "BCAR4 via miR-665/STAT3 axis could promote tumorigenicity in CCR and maintains cancer stem cell stemness." (PMID 34368145, 2021). "Subgroup stratified analysis showed that tumor type, sample size, follow-up months, and survival analysis method did not alter the predictive value of BCAR4 on OS in various cancers." (PMID 31762809, 2019). "Subgroup analysis of prognostic role of lncRNA BCAR4 on OS and RFS in cancer patients." (PMID 31124974, 2019). "Based on their proliferative effect in cancer and stem cells, we hypothesize that the MII oocyte-lncRNAs BCAR4, WEE2-AS1 and TUNAR could be involved in cell division, until the human embryo can transcribe its own factors." (PMID 29396444, 2018). "Furthermore, subgroup stratified analysis showed that tumor type, sample size, and follow-up months, and survival analysis method did not alter the predictive value of BCAR4 on OS in human cancers." (PMID 31762809, 2019). "Although the mechanisms by which BCAR4 can activate EGFR have not been fully elucidated, the contribution of BCAR4 to cancer progression makes this plausible." (PMID 36081848, 2022). "Elevated BCAR4 expression was predictive of unfavorable OS (HR=2.23, 95% CI: 1.84-2.71), but not PFS (HR=1.30, 95% CI: 0.80-2.11) in various carcinomas according to the results." (PMID 31762809, 2019).
tumor (25 papers, 2010 to 2025). "BCAR4 is a strong transforming gene causing estrogen-independent growth and antiestrogen resistance, and induces tumor formation in vivo." (PMID 30459529, 2018). "For patients with metastatic BC who are treated by tamoxifen, relatively high level of BCAR4 mRNA is associated with high degree of tumor malignancy and short survival." (PMID 30459529, 2018). "In patients treated with tamoxifen for advanced disease, higher BCAR4 mRNA levels are associated with an aggressive tumor phenotype and reduced progression-free survival." (PMID 26317614, 2015). "Besides, BCAR4 also causes anchorage-independent cell growth, which promotes tumor metastasis and poor overall survival." (PMID 27732939, 2017). "Some lncRNAs, such as SNHG1 and BCAR4, play significant roles in tumor progression through their interactions with specific microRNAs." (PMID 40868849, 2025). "In terms of clinicopathological characteristics, the high expression levels of six drug resistance-associated lncRNAs, namely, ADAMTS9-AS2, BCAR4, FGD5-AS1, PANDAR, SLCO1C1, and UCA1, were found to be positively correlated with tumor size." (PMID 38927012, 2024). "The index case carrying CD63–BCAR4 fusion also showed highly upregulated BCAR4 mRNA expression in tumour tissue when compared with other patients." (PMID 33204025, 2021). "The tumor growth curve showed significant reduction in the BCAR4 knockdown group compared with shCtrl group." (PMID 33602031, 2021). "Efficient knockdown of BCAR4 in EC109 cells following shRNA interference action was verified by qRT-PCR in tumor tissues." (PMID 33602031, 2021). "For instance, high BCAR4 mRNA levels predict resistance to tamoxifen therapy and poor outcome in ERα-positive BC, reflecting tumor aggressiveness and inducing tumor formation in vivo." (PMID 33602031, 2021). "Mechanistically, BCAR4 participates in tumor progression via sponging miR-139-3p to upregulate ELAVL1 in ESCC." (PMID 33602031, 2021). "The expression level of BCAR4 was obviously increased in clinical ESCC tissues compared with the non-tumor tissues." (PMID 33602031, 2021). "In vivo tumor xenograft study was used to verify the malignancy of CRC cells with inhibition of BCAR4." (PMID 30962766, 2019). "Meanwhile, some researchers consider that BCAR4-based high tumor-specific expression would be used for treating anti-estrogen BC as target." (PMID 30459529, 2018). "We checked the mRNA levels of BCAR4 in 20 pairs of tumor and adjacent normal tissues by RT-qPCR, and found that BCAR4 was upregulated in tumor tissues." (PMID 29190958, 2017). "Further, it was found that patients with high levels of BCAR4 were at increased risk of early recurrence of diseases and suffered low survival rates compared to patients having low levels of BCAR4, reflecting the role of BCAR4 in tumor aggressiveness." (PMID 29299178, 2017). "In sum, BCAR4 promotes tumor cell growth in vitro and in vivo by activating Wnt/β-catenin signaling." (PMID 29190958, 2017). "In clinical BC specimens, BCAR4 mRNA is detectable in approximately 10–27% of cases, depending on the tumor collection and the assay." (PMID 26317614, 2015). "Lapatinib, a clinically approved EGFR/ERBB2 inhibitor, counteracts BCAR4-driven tumor cell growth, a clinical relevant observation." (PMID 26317614, 2015). "Follow-up studies revealed that BCAR4 mRNA levels correlate with tumor aggressiveness in advanced stage BCs and that BCAR4 acts in an ERBB2/3-dependent manner in ZR-75-1 and MCF7 cells." (PMID 26317614, 2015). "High BCAR4 mRNA levels were associated with poor MFS and overall survival, reflecting tumour aggressiveness." (PMID 20859285, 2010). "Additionally, the expression patterns of three lncRNAs were linked to recurrence-free survival (RFS) (BCAR4 and EIF3J-DT) and tumor recurrence (LINC-PINT)." (PMID 38927012, 2024). "BCAR4 overexpression can promote tumor growth by modulating miR-2276/MMP7 axis." (PMID 34937497, 2022).